IL1B (interleukin 1 beta)
Diseases named in the same sentence as IL1B in open-access papers (continued):
Sharing a sentence is not in itself a finding about the gene and the disease.
tumor (continued). "OLT1177 disrupts IL-1β/IL-6/STAT3 axis in TME resulting in reduced tumor growth through attenuating immunosuppressive activities in MDSCs, and the anti-tumor effect is further enhanced in combination with anti-PD-1." (PMID 36932407, 2023). "On ELISA of tumor lysates of core and edge samples, edge lysates demonstrated statistically significant elevations in cytokines TNF-α, IL-1β and IL-6 compared to core lysates." (PMID 37752585, 2023). "Immunohistochemistry and enzyme-linked immunosorbent assay were performed to detect SIRT3 expression and the expression levels of IL-1β, TNF-α, and IL-6, respectively, in tumor tissues." (PMID 37747648, 2023). "Collectively, these results indicate that IL1α, IL1β and IL8 are necessary for 231‐GFP cells to interact with macrophages and subsequently gain the abilities of tumor growth, cancer metastasis, and macrophage infiltration of the tumor sites." (PMID 37551997, 2023). "Moreover, they express effector molecules, which are destined to kill tumor cells, including perforin 1, granzyme B and TNFα, as well as multiple pro-inflammatory cytokines that are characteristic for activated macrophages and Th1 cells, including IL-1β, IL-6, IL-2 and IFNγ." (PMID 37174085, 2023). "On the other hand, IL-1β, IL-6, IL-8, IL-10, IL-12, MCP-1, MIP-1β increased high grade tumor compared to low grade tumor." (PMID 37520880, 2023). "ILC3 is recruited and activated at the tumor site, where it promotes the generation of chemokine CCL20 and proinflammatory cytokine IL‐1β." (PMID 37937304, 2023). "More importantly, overexpression and knockdown experiments showed that IL1α controlled the expression of IL1β and IL8 in TNBC 231‐GFP cells, which indicates IL1α as a critical cytokine in macrophage‐stimulated tumor progression." (PMID 37551997, 2023). "The PGF2 tumor phenotype has elevated CCL2, IL6, IL1A, and IL1B, all of which are secreted by uterine smooth muscle cells treated with PGF2." (PMID 36834607, 2023). "Incubation of BMDM with KrasMUT tumor-conditioned media promoted their differentiation as assessed by flow cytometry for markers MHCII and CD206, and Il1b mRNA and IL-1β protein expression." (PMID 36980752, 2023). "Results of qPCR performed using this mRNA showed that the levels of proinflammatory cytokines, including IL-1β, IL-6, and TNF-α were significantly increased in tumor-bearing mice after DSF treatment." (PMID 37305383, 2023). "In B7H4 positive tumours, a cluster consisting of IL-5, IL-4, VEGFA, M-CSF, IFN-γ, IL-Ra, IL-8, and IL-1β was chosen for further analysis." (PMID 36980202, 2023). "In malignant tumors, tumor cells can activate the inflammatory pathway in normal fibroblasts by secreting cytokines, such as TGF-β1, PDGF, and IL-1β, resulting in the transformation into CAFs." (PMID 36418470, 2023). "Here, we found that lactate, the aerobic glycolysis byproduct released by tumor cells, can directly induce NLRP3 inflammasome activation and promote IL‐1β maturation." (PMID 37009412, 2023). "The tumor-promoting effect of HDM was significantly decreased by heat treatment of the HDM extract and was inhibited by NLRP3, IL-1β, and CCL2 neutralization, or ICS treatment." (PMID 36670473, 2023). "Members of the IL1 family, including IL1B, IL33, and IL18, are upregulated in the GPBAR1 tumors and are generally identified as contributors to tumor immunosuppression." (PMID 36834607, 2023). "The pro-inflammatory cytokines IL-1β, IL-6, and TNF-α are involved in tumor cell proliferation, angiogenesis, and metastasis and seem to strengthen each other’s mode of action, these being stimulated by the same mediators." (PMID 38137862, 2023). "Inspired by this point, we analysed the inflammation in TIOs+NIR1 treated mice, as shown, compared with TIOs+NIR3 treatment, the IL-1β, IL-18 and HMGB-1 release in tumour beds were almost four fifths lower." (PMID 37673934, 2023).
tumor (continued). "Similar to the results obtained from the lung colony formation experiment, knockdown of IL1β in the 231‐GFP cells also had less effects than knockdowns of IL1α and IL8, resulting in the reduction of the tumor size by 39% and tumor weight by 21%." (PMID 37551997, 2023). "In TLN, Caprin-1 suppressed activation of lymphocytes, T cell activation and anti-tumor cytokine and chemokine (IFNG, IL1B, IL21 and TNF) production." (PMID 38082307, 2023). "Treatment of A549 tumor-bearing mice with CA (20 and 40 mg/kg) meaningfully reduced the tumor volume, decreased TNF-α, IL-6, and IL-1β, p-NF-κBp65, and increased Nrf2 and HO-1 in the comparison control group." (PMID 36978983, 2023). "The leak of intracellular IL-1β, lactate dehydrogenase (LDH), and ATP outside the cell was also significantly higher in the nanoinhibitor-treated tumor cells undergoing pyroptosis." (PMID 37316830, 2023). "The release of cytokines IL-1β, IL-6, IL-8, and TNF-α was analyzed in the supernatants of tumor cells (24 h) and CD34+ HSCPs (24, 48, 72 h) after IR (single-dose: 9 Gy) in order to investigate the influence of IEPA on inflammatory responses." (PMID 36903253, 2023). "Based on prior studies implicating the NF-κB pathway in IL-1β–mediated signal transduction, we analyzed this pathway in PDGFB and Nf1 mGBM tumor cell cultures in vitro." (PMID 37733448, 2023). "We analyzed the cytokine milieu of the tumor microenvironment and discovered high levels of the pro-inflammatory cytokines tumor necrosis factor (TNF)-α, interleukin (IL)-1β, and IL-6." (PMID 37461742, 2023). "Consistently, the majority of IL‐1β was expressed in F4/80‐positive Mφ in ID8 and LLC mouse tumor tissues with immunofluorescence (IF) staining." (PMID 37009412, 2023). "We measured the concentrations of inflammatory cytokines in tumor tissue 3 days after bacterial treatment and observed that the levels of inflammatory cytokines (TNF-α and IL-1β) were increased in the bacterial treatment groups." (PMID 37908720, 2023). "When delivering and specifically releasing an active GSDMA3 fragment into tumor cells, GSDMA3-NT similarly triggered CAP as well as IL-1β production." (PMID 36742298, 2023). "Glucose-induced H3 ubiquitination target genes, such as IL-1α, IL-1β, and glutamate-cysteine ligase modifier (GCLM) subunit, are also important factors for tumor sphere formation." (PMID 37164974, 2023). "The ELISA results illustrate the robust induction of IL-1β, IL-18 and HMGB1 production, an indicator of pyroptosis-induced ICD, in both tumor and serum samples following treatment with GSDMBNT mRNA@LNPs alone or in combination with a-PD1." (PMID 37454146, 2023). "Thus, we sought to determine whether tumor cells can trigger IL‐1β secretion from Mφ." (PMID 37009412, 2023). "Taken together, these results show that IL‐1β secreted by Mφ stimulates CCL2 secretion in tumor cells, which in turn boosts Mφ infiltration, thus further increasing PD‐L1 expression in tumor cells and orchestrating tumor immunosuppressive microenvironment." (PMID 37009412, 2023). "Meanwhile, IL‐1β induced CCL2 secretion from tumor cells and exhibited a strong ability to recruit Mφ into the tumor site." (PMID 37009412, 2023). "Tumoral subsets, including MDSC and TAMs, are known to release IL-1β and induce CAFs to mediate inflammation." (PMID 37893079, 2023). "LPS/ATP increased the size of the tumor spheres in MDA-MB-231 cells, which had a high NLRP3 expression and IL-1β release." (PMID 36902278, 2023). "In the present study, we found that the level of proinflammatory cytokines including IL-1β, IL-6 and TNF-α were significantly increased in tumor-bearing mice after DSF treatment." (PMID 37305383, 2023). "Interleukin-1β (IL-1β) present in the TME recruits myeloid cells, limits anti-tumor effects of chemotherapy, and promotes tumor invasiveness and immunosuppression." (PMID 36260158, 2023).
tumor (continued). "FAO-dependent ROS generation activates NLRP3 inflammasome to release IL-1β from TIME M2 macrophages, supporting tumor cell migration and metastasis." (PMID 37275901, 2023). "To further verify this notion, we examined CD68, IL‐1β, CD8, and granzyme B, a cytotoxic executor, in clinical tumor tissues of HG‐SOC patients with fluorescence multiplex immunohistochemical analysis." (PMID 37009412, 2023). "Another potential target is pro-inflammatory cytokines and chemokines, such as IL-6, IL-8, IL-1β, and TNF-α, which contribute to the promotion of tumor growth, angiogenesis, and metastasis." (PMID 37760801, 2023). "Under the influence of GBM, GAMs are a major source of inflammatory cytokines (e.g., IL-1β, IL-8, IL-10) and chemokines (e.g., CCL2, CCL4, CCL5) that support GBM growth and mitigate anti-tumor immune function." (PMID 37368789, 2023). "Heteroctenus junceus scorpion venom, depending on the concentration and incubation time, promotes a decrease in the cytokines IL-6, IL-1β and IFN-γ; as well as an increase in TNF-α and IL-12 in the supernatant of the F3II tumor cells." (PMID 38137888, 2023). "CXC motif chemokine ligand 2 (CXCL2) released by tumor cells, which in turn activates CXC chemokine receptor 2 (CXCR2), and IL-6, IL-8, and IL-1β recruit tumor-infiltrating MDSCs inducing epithelial–mesenchymal transition (EMT) and metastasis." (PMID 36831498, 2023). "Meanwhile, both Se-PC PDT and PC PDT treatment inhibited tumor initiation and metastasis by downregulating the expression levels of Vegfa, Mmp13 and Serpinel via the HIF-1 pathway and IL-1b and Nfkbia via the NF-κB and TGF-β signaling pathways." (PMID 37994159, 2023). "The obese tumor microenvironment recruits macrophages that activate the NOD-like receptor 4 (NLRC4) inflammasome, leading to interleukin-1β (IL-1β) activation." (PMID 36670988, 2023). "We assessed the concentrations of proinflammatory factors (IL-1β, IL-18, HMGB1) in tumours or in serum." (PMID 37673934, 2023). "The NOTCH1 pathway forms a positive feedback loop between the tumor cells and TAMs, and its overexpression increases the expression of NOTCH1 and JAGGED1 and upregulates the expression of IL-1β and CCL2, thereby leading to M2 polarization." (PMID 37894541, 2023). "IL-1β, IL-4, IL-10, IL-13, and TGF-β1, which are secreted by TAMs, are of significance in promoting tumor growth, EMT, or CSC formation." (PMID 36624542, 2023). "IL-1β is abundant in the TME and plays a crucial role in promoting tumour growth and inducing tumour immunosuppression." (PMID 37742025, 2023). "Tumor tissue levels of CCL3 (MIP-1α) and IL-1β displayed significant positive correlation with the amount of HIF-1α in the tumor." (PMID 38273861, 2023). "Nigericin displayed an anti-tumor impact in tumor cell lines with modest NLRP3 stimulation and IL-1β and IL-18 production." (PMID 37715239, 2023). "Indirectly, mitoxantrone induces anti-tumor immunity against fibrosarcoma, characterized mainly by enhanced CD8+ T cell activation, through myeloid cell-derived IL-1β produced by NLRP3 inflammasomes." (PMID 36932407, 2023). "The inflammatory cytokines including IL-1β, IL-6, IL-8, and CCL-5 that are induced by NF-kB promote tumor growth through the induction of cell proliferation." (PMID 37340387, 2023). "IL-1β and IL-18 have dual roles in the TME and distal tissues, and exert varying effects at different stages of tumor development." (PMID 35856558, 2022). "Specially, lactate accelerates glycolysis, angiogenesis, and chronic inflammation by promoting IL-1β, IL-8, VEGF, and NF-κB signals, which ensures sufficient oxygen and nutrient supply for tumor cell proliferation." (PMID 35572545, 2022). "Recent research found that PDAC cell-derived IL-1β also plays a critical role in promoting PSC activation and tumour progression." (PMID 35986089, 2022).
tumor (continued). "By increasing the infiltration of CD3+/CD4+ T cells and DX5+ NK cells in the tumor area, the expression of cytokines such as IL-1β, TNF-α, IFN-γ, GM-CSF were increased, and the anti-tumor effect was also observed." (PMID 35757741, 2022). "In this sense, the M1 phenotype releases IL-12, IFN-γ, TNF-α, IL-1β, ROS, and nitric acid, hence promoting the recruitment and activity of NK cells and CD8 + T cells in the tumor microenvironment to induce an anti-tumor immune function and inflammation." (PMID 35565420, 2022). "Exposure to PM2.5 resulted in an increased number of tumor nodules and elevated expression of MMP1, IL-1β, VEGF, and angiogenesis factors in a tumor-bearing mouse model." (PMID 35448437, 2022). "Many osteoclast-activating factors (IL-6, IL-1β, HGF and TNF-α) are released by the mutual interactions of tumour and bone marrow cells with a major involvement of RANKL, the decoy receptor OPG, and MIP-1α a." (PMID 36362718, 2022). "As the key trigger of pyroptosis, the NLRP3 inflammasome activated by dying tumor cells can stimulate DCs, thus effectively priming CD8+ T cells by secreting IL-1β, and thereby inducing a strong and durable tumor immune response." (PMID 36513682, 2022). "Consistently, THP-1 macrophages treated with CM of tumor cells or CM of olaparib-treated tumor cells showed significantly up-regulated IL6, IL1B and CXCL1 gene expression." (PMID 35641483, 2022). "Tumor cells induce various inflammatory cytokines, including TNF-α, IL-1β, IL-6, IL-17/18, and IL-23, and growth factors (G-CSF, GM-CSF, and IL-3) to generate neutrophil production and confirm their survival." (PMID 36091114, 2022). "Zinc enriches the microbiome in Prevotella, Proteobacteria and Actinobacteria and improves the function of the immune system by increasing the level of pro-inflammatory cytokines such as IL-1β, IL-2, IL-6, TNF-α and IFN-γ in the tumor environment." (PMID 36428677, 2022). "The activated mast cells also produce IL1β, IL6, IL8, IL13, TGFβ, TNFα, PDGF, and VEGF for promoting tumor growth and metastasis directly, and also indirectly by provoking angiogenesis and immune chaos." (PMID 36211375, 2022). "These tumor-promoting effects were mediated by the production of IL-1β and the recruitment of immunosuppressive MDSC into the tumor." (PMID 36555392, 2022). "Another study has revealed that the increased secretion of CRCSC-exos was accompanied by elevated tumor infiltration of myeloperoxidase neutrophils, which promotes tumorigenesis of CRC cells via IL-1β." (PMID 35461336, 2022). "TAMs and CAFs were classified according to their tumor origin and high expression of SPP1, C1QB, IL1B, S100A8, S100A9 and type I collagens (COL1A1 and COL1A2)." (PMID 36209225, 2022). "Being an immunogenic form of cell death, pyroptosis produces proinflammatory cytokines such as IL-1β, IL18 to facilitate the infiltration of immune cells to the immunosuppressive TME, demonstrating it can be utilized in anti-tumor therapy." (PMID 35432318, 2022). "Together, these data reveal a role for neutrophil-derived IL-1β in promoting iCAF polarization and inducing CAF-tumor cell IL-6/STAT3 signaling in the PDAC TME, which is a central mediator of chemoresistance." (PMID 36107485, 2022). "In one study, lower concentrations of ellagic acid decreased IL-1β, IL-6, IL-1Ra, and IL-10 production by PBMC incubated with a tumor cell line (HT-29), whereas higher concentrations inhibited the production of all cytokines examined, except IFN-γ." (PMID 35745713, 2022). "As displayed by RT-qPCR and Western blot analysis, IL-1β treatment led to upregulation of lncRNA CHRF and Myd88 along with downregulation of miR-489 in tumor tissues." (PMID 35711847, 2022). "Parallel to the analysis of BCRP expression, the changes in the levels of IL-1β, TNF-α, and IL-10 cytokines in peripheral blood in the control and tumor-bearing animals were investigated." (PMID 35053477, 2022).
tumor (continued). "Important immunological checkpoints involved in tumor immune escape include CD274, IL1B, IL1A, PDCD1, PDCD1LG2, and SIRPA." (PMID 35401746, 2022). "Using value of IOD, quantification of immunohistochemical analysis showed that protein expressions of CYBB, IL1A, IL1B, and SLC25A5 were significantly higher in CESC tissues than in adjacent non-tumor tissues (P < 0.001)." (PMID 36253777, 2022). "Carmi and colleagues discovered the relationship between IL-1β and VEGF in early angiogenesis during tumorigenesis, confirming how inflammation and tumor angiogenesis work together." (PMID 35681719, 2022). "IL1β and CCL20 have been found to be important cytokines which lead to recruitment of ILC3s to the tumor site." (PMID 35663967, 2022). "Th17 cells highly produce pro-inflammatory molecules, such as IL17, IL1β, IL6, IL23, and nitric oxide (NO), and promote tumor progression directly, and also indirectly via inducing angiogenesis." (PMID 36211375, 2022). "The consequent overproduction of key cytokines (IL-1β, IL-6, and TNF-α) played an important role in the exacerbated tumor burden in the AOM/DSS + Abx + Akk group." (PMID 36312913, 2022). "Our work also emphasizes the sequential roles of IL-1β and VEGF-A; while systemic delivery of IL-1β would favor the production of myeloid cells, VEGF-A would shape the tumor microenvironment." (PMID 36104342, 2022). "Although M1 macrophages have been considered to exert an anti-tumor role, M1 macrophages my promote PD-L1 expression in HCC tumor cells, highlighting the potential role of M1 macrophages in tumor promotion through IL-1β pathway." (PMID 35158892, 2022). "Finally, KPC tumor cells demonstrated significantly higher pSTAT3 expression when incubated with conditioned media (CM) from intratumoral neutrophil-CAF co-cultures alone compared with CM from neutrophil-CAF co-cultures treated with either anti-IL-1β or anti-IL-6 neutralizing antibodies." (PMID 36107485, 2022). "Except for inducing cell death, some inflammatory factors that are produced by pyroptosis, such as IL-1β, IL18, and HMGB1, can activate the cancer-promoting signaling pathways including MAPK and VEGF pathways, which accelerates tumor growth." (PMID 35000541, 2022). "M1-TAMs play a key role in killing tumor cells by producing reactive oxygen/nitrogen species (ROS/RNS) and pro-inflammatory cytokines such as IL-1β, IL-6, and TNF-α, and thus M1-TAMs are macrophages with anti-tumor effects." (PMID 35479325, 2022). "The tumor concentrations of periostin were correlated with tumor levels of VEGF-A, IFN-γ, IL-1β and TNFα." (PMID 35056404, 2022). "Similar to IL1β, HMGB1 is also involved in dendritic cell (DC) maturation, tumor antigen presentation, neutrophil polarization, and cytokine release in TME." (PMID 35432318, 2022). "The tumor and mesenchymal cells in the TME express multiple chemokines and cytokines (e.g., CXCL1, CXCL2, CXCL5, CXCL6, IL1, IL1β, IL6, IL8, IL17, TNFα, and G-CSF), which are regulated by KRAS, SNAIL, and NOTCH signaling." (PMID 35504900, 2022). "PCR results showed that HPP promoted the expression of IL-1β, IL-6 and TNF-α mRNA in macrophages in the tumor microenvironment." (PMID 35603205, 2022). "Molecules such as TNF-α, IL-1β, IL-6, IL-21, TGF-β, and IL-23 which are secreted by the immune and tumor cells, accumulated in the TME, can play a vital role in inducing Th17 development." (PMID 35248028, 2022). "In turn, activated adipocytes secrete chemokines (CCL2, and CCL5), cytokines (IL-1β, IL-6, TNF-α), and angiogenic factors (VEGF), all required for the promotion of tumor growth, angiogenesis and metastasis." (PMID 35493456, 2022). "MiR-155 induced by inflammatory cytokines, such as IL-1β and TNFα, mediates mesenchymal transition of GBM tumor cells and GBM growth." (PMID 35572545, 2022). "Significant increases in IFNG, IL‐18, IL‐1β, IL‐8, TNF‐α, TLR4, MyD88, and NF‐κB levels were found in the P. copri and tumour control groups." (PMID 35735103, 2022).